MTOR (mechanistic target of rapamycin kinase)
Diseases named in the same sentence as MTOR in open-access papers (continued):
Sharing a sentence is not in itself a finding about the gene and the disease.
breast cancer (continued). "Further study is needed to determine the effect of clinically relevant doses of PI3K/mTOR pathway inhibitors in vivo, and their effect on eEF2K low- and high-expressing hormone receptor-positive breast cancers." (PMID 23102376, 2012). "The direct targets of the miR-99 family are the chromatin remodeling factors SMARCA5, SMARCD1 and the growth regulatory kinase mTOR, which is also an important pathway activated in breast cancer." (PMID 22438871, 2012). "Recognition of rapamycin’s anti-tumor target of the mTOR pathway led to the development of analogues of rapamycin as chemotherapeutic agents against solid tumor types, including breast cancer." (PMID 23369283, 2012). "The mammalian target of rapamycin (mTOR) signaling pathway, which is upregulated in many cancers, was stimulated in breast cancer cultured cells treated with AA." (PMID 22811918, 2012). "Aberrant activation of the PI3K/Akt/mTOR pathway has been found in many types of cancer and thus plays a role in breast cancer proliferation and anti-cancer resistance." (PMID 23065768, 2012). "The material from this trial will constitute a unique resource to determine the genomic and epigenomic determinants of sensitivity to concurrent mTOR inhibition and endocrine treatment in breast cancer." (PMID 22970424, 2012). "In T47D breast cancer cells, pathways involving endocytosis, ubiquitin mediated proteolysis, mTOR signaling, Wnt signaling, and apoptosis were specifically overrepresented." (PMID 22272226, 2012). "Combinatory effects of gemcitabine and inhibitors targeting PI3K-Akt-mTOR pathway in human pancreatic and breast cancer cells." (PMID 22590527, 2012). "The Her-2/AKT and mTOR pathways are targets accessible to new inhibitors; trastuzumab has demonstrated its efficacy in Her-2/neu-amplified breast cancer." (PMID 22879924, 2012). "In carcinomas, the PI3K/AKT pathway is well characterized; and the PI3K/Akt/mTOR pathway has been shown to be a target for cancer therapy including breast carcinoma." (PMID 23056620, 2012). "The sensitizing effect of PIK3CA mutation to the dual PI3K/mTOR inhibitor BEZ235 and to a selective Akt inhibitor in breast cancer cells has already been reported." (PMID 21362200, 2011). "Here, we show that the EGFR inhibitor gefitinib and the mTOR inhibitor RAD001 when used in combination improve effectiveness of the treatment in HER2 overexpressing breast cancers that results in impediment of cancer growth." (PMID 21961653, 2011). "Accumulating evidence suggests that PI3K/AKT/mTOR promote breast cancer cell survival and resistance to chemotherapeutics such as trastuzumab (a blocking antibody to Her-2) and tamoxifen." (PMID 21119656, 2011). "This leads to an inhibition of the mammalian target of rapamycin (mTOR) pathway and a decrease in protein synthesis, inhibition of adhesion, migration and invasion of breast cancer cells." (PMID 21774820, 2011). "In the studies presented in this report, we have examined the effects of constitutive activation of Akt on the sensitivity of MCF-7 breast cancer cells to chemotherapeutic- and hormonal-based drugs as well as mTOR inhibitors." (PMID 21730367, 2011). "Here, we assessed feasibility of combining the EGFR inhibitor gefitinib and the mTOR inhibitor everolimus (RAD001) for treating HER2 overexpressing breast cancers with different sensitivity to TZ." (PMID 21961653, 2011). "To conclude, ERα/c-Src/PI3K/Akt/mTOR signals elevate the levels of HIF-1α in response to oestrogen in ERα+ breast cancer lines." (PMID 21897387, 2011). "Inhibition or genetic deletion of mTOR or S6K1 in mouse embryonic fibroblasts or breast cancer, but also in murine diabetes models resulted in Ras-MAPK activation via insulin receptor substrate-1 (IRS)." (PMID 22110663, 2011). "Many studies suggested PI3K/AKT/mTOR survival pathway plays an important role in cisplatin resistance in ovarian cancer, lung cancer and breast cancer." (PMID 22096562, 2011).
breast cancer (continued). "The PLD2 point mutation has been found in breast cancer cells, and PLD2 overexpression confers a survival signal attributed to an increase in basal mTOR activity." (PMID 20711340, 2010). "This study highlights the potential role of OPN to induce ICAM-1 expression through mTOR/p70S6 kinase pathway in breast cancer cells." (PMID 20459645, 2010). "AKT phosphorylates FRAP1 (mTOR) at S2448 increasing FRAP1 kinase activity, and decreased FRAP1 S2448 phosphorylation was observed in the breast cancer cell lines." (PMID 20604938, 2010). "It was suggested that this dual action of metformin (insulin reduction and mTOR inhibition) makes it a particularly attractive target for evaluation in breast cancer as well as some other, e.g. colon cancer." (PMID 21084729, 2010). "The mTOR pathway is highly involved in breast carcinoma pathogenesis and adjuvant therapy resistance." (PMID 19680458, 2010). "mTOR is aberrantly activated in a significant portion of breast cancers and is a promising target for treatment." (PMID 19778445, 2009). "We sought to identify genes differentially expressed in response to treatment with rapamycin in MDA-MB-468 cells, a PTEN-null human breast cancer cell line with constitutive activation of PI3K/Akt/mTOR signaling." (PMID 19778445, 2009). "This supports the central role of mTOR signaling in breast cancer biology and provides further impetus to pursue mTOR-targeted therapies for breast cancer treatment." (PMID 19778445, 2009). "The phosphatidylinositol 3-kinase (PI3K)/Akt/mTOR signaling pathway in particular is deregulated in many cancers, including breast cancer." (PMID 19778445, 2009). "The mTOR pathway is activated in breast cancer and has become a promising target for breast cancer therapy." (PMID 19778445, 2009). "mTOR inhibitors have shown clinical activity in patients with advanced breast cancer and are being actively investigated in this setting in combination with other agents that have shown clinical activity in metastatic breast cancer (MBC)." (PMID 19860903, 2009). "In breast cancer, p-mTOR expression is predominantly detected in the cytoplasm and is significantly associated with short RFS, but does not correlate with any clinicopathological factors, including stage, histological grade, and lymph node involvement." (PMID 19223902, 2009). "In this study, we applied RMI to independent primary breast cancer data sets to confirm the importance of mTOR signaling in breast cancer biology." (PMID 19778445, 2009). "Sirolimus and other mTOR inhibitors are currently in clinical trials, and their anti-tumor efficacy in breast cancer in preclinical models has been demonstrated." (PMID 19225562, 2009). "This agrees with the results of studies of the prognostic role of mTOR pathway activation in breast cancer using immunohistochemistry." (PMID 19778445, 2009). "The mTOR protein expression data with phospho-specific mTOR antibody indicate inhibition of mTOR phosphorylation with 50 μM biochanin A treatment (42.26 ± 12.18; P < .05) in SK-BR-3 breast cancer cells." (PMID 20169097, 2009). "Rapamycin and its analogs, which are currently in late-stage clinical trials in breast cancer, inhibit mTOR kinase, a key regulator of cyclin D1." (PMID 19077306, 2008). "Recently, the importance of the dual suppression of both EGFR and mTOR expressions was shown when the proliferation of breast cancer was synergistically reduced after the inhibition of both EGFR and mTOR expressions." (PMID 18797454, 2008). "Rapamycin has a direct anti-tumor effect on Wnt-1 breast cancer in vivo that involves inhibition of the mTOR pathway at doses that also suppress host immune responses." (PMID 18570671, 2008). "We also compared the individual gene expression profiles between Ly294002- and rapamycin-treated and RPS6KB1-suppressed BT-474 and MCF-7 breast cancer cell lines to identify genes downstream of PI3K/mTOR/p70S6K pathway." (PMID 18652687, 2008).
breast cancer (continued). "The inhibition of PI3K/mTOR pathway by small molecule inhibitors led to similar gene expression alterations across several breast cancer cell lines with different biological outcomes." (PMID 18652687, 2008). "The inhibition of PI3K/mTOR pathway with Ly294002 and rapamycin led to similar gene expression alterations in different breast cancer cell lines." (PMID 18652687, 2008). "Consistently, both, Trastuzumab and the mTOR-inhibitor Rapamycin, inhibited the growth of Her+breast cancer cell lines." (PMID 19077306, 2008). "Five breast cancer cell lines were treated with PI3K/mTOR pathway inhibitors, including two cell lines that were also inhibited with three RPS6KB1 siRNAs, since these two cell lines show a high-level expression of p70S6K." (PMID 18652687, 2008). "Inhibition of the mTOR pathway is effective in inhibiting tumor growth in cell lines and in xenograft models of erbB2-overexpressing breast cancer and is currently under investigation in clinical trials." (PMID 19077306, 2008). "The sensitization of Her+ breast cancer cells to Rapamycin by Pin-inhibition was expected as Pin1 regulates signaling both up- and downstream from mTOR, thereby likely rendering these cells more vulnerable to growth arrest as a consequence of Pin1 inhibition." (PMID 19077306, 2008). "Our aim was to determine p70S6K and PI3K/mTOR/p70S6K pathway dependent gene expression profiles by microarrays using five breast cancer cell lines with predefined gene copy number and gene expression alterations." (PMID 18652687, 2008). "Pin1 inhibition alone and in conjunction with mTOR inhibition suppresses the growth of Her2+ breast cancer cells." (PMID 19077306, 2008). "Our aim was to identify genes that are transcriptionally altered due to PI3K/mTOR/p70S6K pathway inhibition in breast cancer cells using RNAi and small molecule inhibitors." (PMID 18652687, 2008). "Expression of 17 genes was altered in BT-474 and MCF-7 breast cancer cell lines in response to both PI3K or mTOR inhibition and p70S6K inhibition with at least two siRNAs." (PMID 18652687, 2008). "The results from Chen and colleagues are intriguing and in this study, we have used clinical tissues to evaluate the expression of PLD1 with phospho-Akt and phospho-mTOR in breast carcinomas to help facilitate patient selection for mTOR-targeted therapies." (PMID 17726467, 2007). "Second, constitutive activation of the PI3K/Akt pathway frequently occurs in breast cancer and some of its oncogenic effects are mediated through the mTOR pathway." (PMID 16859513, 2006). "Recent studies have shown that activation of the PI3K/Akt pathway and its downstream mTOR signaling pathway promote, at least in part, the proliferation rate of breast cancer by down-regulating p27 nuclear protein levels." (PMID 16859513, 2006). "The mammalian target of rapamycin (mTOR) is a downstream mediator in the phosphoinositol 3' kinase (PI3K)/Akt pathway that down-regulates p27 levels in breast cancer." (PMID 16859513, 2006). "Although increased phosphorylation of AKT and mTOR in breast cancer have been recently reported, limited number of studies has contrasted the phosphorylation profiles of large panel of protein kinases among normal and invasive breast cancer tissues." (PMID 16288304, 2005). "However, our observation as frequent deregulation in the PDK-1/AKT/mTOR/p70S6K signalling pathway and its prognostic role in breast cancers implicated the notion of using inhibitors to impair this pathway and to provide additional strategy to treat breast cancer." (PMID 16288304, 2005). "In this study, we characterized growth dynamics, tissue architecture, and mammalian target of rapamycin (mTOR) pathway activity in a 3D bioprinted breast carcinoma model of T47D cell line and compared these features with conventional two-dimensional (2D) monolayer cultures." (PMID 42253937, 2026).
breast cancer (continued). "For example, CpGs exhibiting higher methylation levels in female cetaceans were linked to genes such as the mTOR-related RRAGA on chromosome 9 (cg04565674, Meta P = 1.0 × 10–159) and the breast cancer-related gene BCAR3 on chromosome 1 (cg06678289, Meta P = 4.6 × 10–36), among others." (PMID 39900928, 2025). "In summary, the combination of IVM and MET promotes the production of reactive oxygen species, causes intracellular oxidative stress and mitochondrial dysfunction, and inhibits the activation of the PI3K/Akt/mTOR signaling pathway, thus inducing the necrosis and autophagy of breast cancer cells." (PMID 40699802, 2025). "Thus, we started to explore the potential impacts of hSPAR on mTOR activation in breast cancer cells, by investigating downstream consequences of mTOR signaling in MDA-MB-231 cells in the presence of hSPAR." (PMID 39875724, 2025). "Consequently, targeting key nodes within the PI3K/AKT/mTOR (PAM) pathway represents a promising therapeutic strategy to improve clinical outcomes in patients with advanced breast cancer." (PMID 40535135, 2025). "After integrating the results from the cellular experiments, high-throughput sequencing, and KEGG analysis, we hypothesized that alterations in the mTOR-related pathway are crucial for the regulatory effects of shikonin on breast cancer progression." (PMID 40949144, 2025). "Therefore, to further investigate how FolTAC-mediated HER2 degradation affects downstream signaling, we focused on the PI3K/AKT/mTOR pathway as HER2 is known to activate key regulatory nodes crucial for breast cancer cell survival and proliferation." (PMID 41038820, 2025). "One study has indicated that dysregulation of the TME may be involved in resistance to mTOR inhibitors in non‐breast cancer patients, but its relevance in HR+/HER2− breast cancer remains insufficiently explored." (PMID 41322031, 2025). "In this study, proteomic sequencing was used to explore whether Ad-VT affects changes in the mTOR/S6K signalling pathway and induces the apoptosis of breast cancer cells." (PMID 40453070, 2025). "The PI3K/AKT/mTOR signaling pathway, critically involved in tumor growth, proliferation, metabolism, and migration, represents one of the most frequently dysregulated pathways in breast cancer therapeutics." (PMID 40421216, 2025). "Similar to MDA-MB-231 cells, the effects of hSPAR on SLC38A2, P27KIP1, mTOR signaling, and cell proliferation were also observed in breast cancer MCF7 cells (Luminal-A subtype) (Fig. EV4I–L) and MDA-MB-468 cells (triple-negative subtype) (Fig. EV4E-H), but not in HEK293T cells (Fig. EV4A–D)." (PMID 39875724, 2025). "Ad-VT can significantly increase the apoptosis level of breast cancer cells, which may be induced by the mTOR/S6K signalling pathway." (PMID 40453070, 2025). "Breast cancer cells can also acquire resistance to paclitaxel by switching from apoptosis to autophagy, which results in downregulation of the mammalian target of rapamycin (mTOR) pathway along with an increased ability of breast cancer cells to survive under stress conditions." (PMID 39863855, 2025). "As IPA events often produce truncated protein products with altered functions, the newly identified unannotated IPA proteins regulated by mTOR signaling may contribute to breast cancer progression." (PMID 41218079, 2025). "Taken together, our results suggest that the molecular mechanism of action of DMDD may involve the enhancement of breast cancer autophagy through the PI3K/Akt/mTOR signaling pathway by mediating ROS expression." (PMID 39648951, 2025). "Similarly, SGK3 expression was also markedly higher in luminal breast cancer patients who were resistant to a PI3K/mTOR inhibitor NVP-BEZ235 as estimated by the DeepDR analysis." (PMID 40303291, 2025). "However, GDC-0084 and GDC-0068 have demonstrated the capacity to overcome this hurdle by inhibiting the PI3K-Akt-mTOR pathway and exhibiting potential to treat breast cancer brain metastasis." (PMID 39979279, 2025).
breast cancer (continued). "Additionally, the upregulation of CMTM6 causes trastuzumab resistance and promotes breast cancer proliferation by increasing HER2 expression through the manipulation of downstream MAPK and PI3K/AKT/mTOR signaling pathways." (PMID 40227634, 2025). "Moreover, GAS5 acts as a tumor suppressor in breast cancer through modulation of the PI3K/AKT/mTOR pathway and participation in Wnt/β-catenin signaling." (PMID 39958058, 2025). "Accordingly, GW405833 may interfere with breast cancer and osteoblast interaction by manipulating the AKT/mTOR pathway both in breast cancer and in osteoblast." (PMID 39980332, 2025). "mTOR inhibitors have been used clinically for over 20 years as post-transplantation immunosuppressants and antineoplastic agents for various malignancies, including breast cancer, and have demonstrated long-term safety." (PMID 39819881, 2025). "Combination with drugs that target CDK4/6, CYP17A1, or the PI3K/AKT/mTOR pathway, immunotherapies, or conventional treatments such as chemotherapy and radiotherapy may enhance the efficacy of breast cancer treatment." (PMID 39851328, 2025). "The mTOR inhibitors may provide additional therapeutic benefits beyond endometrial protection in patients with breast cancer receiving tamoxifen." (PMID 39819881, 2025). "A recent study showed that mTOR inhibitors can extend survival in patients with advanced breast cancer or metaplastic triple-negative breast cancer, indicating that drugs targeting the PI3K/AKT/mTOR pathway may benefit MPBC patients." (PMID 40421084, 2025). "For example, compensatory activation of MEK and/or AKT has been shown to limit mTOR/PI3K inhibitor therapy in prostate and breast cancer cell lines and patient tumor samples, which could be reversed by combined inhibition of mTOR/PI3K and AKT." (PMID 40568132, 2025). "Consequently, co-targeting mTOR with CDK4/6 inhibitors has been explored in cancers including breast cancer." (PMID 40282469, 2025). "In addition, interactions between amino acid metabolism and signaling pathways, such as the mTOR pathway, further emphasize the importance of reprogramming amino acid metabolism in regulating breast cancer cell growth, proliferation, and survival." (PMID 39973065, 2025). "Mechanistically, they reported that MDSCs induce the EMT in breast cancer cells by activating the PI3K/AKT/mTOR signaling pathway and increasing the expression of matrix metalloproteinases (MMPs), thus increasing the invasion and metastatic potential of breast cancer cells." (PMID 40452814, 2025). "By re-establishing PTEN expression and inhibiting the pI3K/Akt/mTOR pathway, VC may sensitize breast cancer cells to conventional therapies, potentially overcoming resistance mechanisms." (PMID 40149617, 2025). "Moreover, it has been found that DHA enhanced the function of LKB1, the target of AMPK, inhibiting the glycolytic enzymes and the mTOR signaling in breast cancer cell lines." (PMID 39863855, 2025). "Moreover, it was discovered that LY294002 (PI3K inhibitor) treatment inhibited the level of PI3K, as well as the levels of AKT and mTOR in human breast cancer cells." (PMID 40559415, 2025). "Furthermore, quercetin has the potential to induce autophagy and is effective in treating breast cancer by inhibiting the Akt-mTOR pathway in glycolysis and cell motility." (PMID 40427522, 2025). "Interestingly, breast cancer and SSc share select molecular pathways, including hyperactivation of the mammalian target of rapamycin (mTOR), phosphatidylinositol 3-kinase (PI3K), and transforming growth factor beta (TGF-β)." (PMID 40416966, 2025).